IL6 (interleukin 6)
Diseases named in the same sentence as IL6 in open-access papers (continued):
Sharing a sentence is not in itself a finding about the gene and the disease.
Obesity (continued). "It is well known that the increased IL6 and TNFα circulating levels in obese patients have led to the conclusion that obesity is characterized by a subjacent chronic low-grade inflammation." (PMID 26694359, 2015). "The pre-acupuncture results showed significant difference between the three grades of obesity and the controls regarding TNFα, IL-6 and hsCRP." (PMID 27275202, 2015). "Conversely, women afflicted with PCOS endure a state of hyperandrogenism which results in increased adiposity, leptin, inflammatory markers TNFα and IL6, and obesity independent decreases in adiponectin." (PMID 26317527, 2015). "Further, adipocytes themselves secrete leptin and IL-6 after the macrophage infiltration and further increase the inflammatory response due in obesity." (PMID 26217222, 2015). "Second, this study elucidates the obesity-related changes in IL-6R/IL-6 together with other inflammatory mediators/ markers." (PMID 26200663, 2015). "Previous studies have suggested that TNF-α and IL-6 are involved in obesity-related insulin resistance and atherosclerosis." (PMID 26714835, 2015). "Higher levels of glycosylated Hb, CRP, IL-6, and fibrinogen, obesity, waist circumference, presence of hypertension grade 2, and AF were significantly related to poor general health in the total sample." (PMID 26121035, 2015). "Serum IL-6 concentrations have been positively correlated with obesity, insulin resistance, T2D, and cardiovascular disease." (PMID 26217222, 2015). "Obesity is often considered a systemic inflammatory condition with increased levels of inflammatory cytokines, including tumor necrosis factor-alpha and interleukin-6." (PMID 25890172, 2015). "It is well established that circulating pro-inflammatory cytokines [e.g. tumor necrosis factor alpha (TNF-α), interleukin 6 (IL-6)] are induced in obesity and these pro-inflammatory cytokines play a crucial role in the development of metabolic syndrome." (PMID 25861245, 2015). "Several specific inflammatory factors have been linked to both obesity and AD including leptin, TNF-α and IL-6." (PMID 26217222, 2015). "We also reported that, in lean animals, EWAT exposed to IH became pathological, behaving like excess fat in obesity, as it exhibited increases in macrophage recruitment and secretion of IL-6 and TNF-α." (PMID 25873766, 2015). "Elevated plasma levels of inflammatory cytokines (including interleukin (IL)-1β, tumor necrosis factor (TNF)-α, IL-6 and C-reactive protein) have been reported in obese patients and different animal models of obesity." (PMID 26190966, 2015). "Obesity-induced chronic microinflammation is characterized by increased production of proinflammatory cytokines such as IL6 that in turn induces CRP production in the liver and secretion into the blood." (PMID 25922641, 2015). "IL-6 levels are elevated in obesity and positively correlate with BMI, and a role for IL-6 in tumorigenesis has been demonstrated in IL-6-deficient animal models that do not develop tumors." (PMID 25019059, 2014). "The different strength of the association of PI/I values with obesity and CRP levels in men and with IL-6 in women is difficult to be interpreted and would be likely clarified at the follow-up analysis." (PMID 25347846, 2014). "A main source of ROS is the increased exposure of target tissue to inflammatory cytokines such as IL-1, TNF, and IL-6 which are increased in obesity." (PMID 25140176, 2014). "Circulating levels of IL-6 are increased in obesity, and it has been proposed that IL-6 contributes to the pathogenesis of IR in different disease states." (PMID 24686488, 2014). "The development of obesity in IL-6 knockout mice further reinforces the key role of this cytokine in controlling lipid metabolism." (PMID 24667661, 2014).
Obesity (continued). "Obesity accompanies chronic systemic inflammation, characterized by pro-inflammatory cytokines including IL-6 and tumor necrosis factor-α (TNFα), which are also known to accelerate insulin resistance and other metabolic abnormalities of obesity." (PMID 25144367, 2014). "The representative inflammatory cytokines, TNF-α and IL-6, were increased under the obesity condition." (PMID 24879081, 2014). "Excessive production of IL-6, as an adipokine, in obesity and diabetes, has an adverse effect on glucose metabolism and insulin sensitivity." (PMID 24563869, 2014). "It is well established that obesity is associated with activation of JNK stress kinase and enhanced inflammatory response as monitored by the endogenous levels of IL-6, TNF-α, RANTES and CCR5 receptor in the adipose tissue." (PMID 24986468, 2014). "The major source of systemic IL-6 is adipose tissue, and reducing fat mass in obesity reduces circulating IL-6 levels." (PMID 24686488, 2014). "This study aimed to analyse the impact of obesity in type 2 diabetes (T2D) on adipocytokines (adiponectin, leptin and resistin) and inflammatory markers (TNF-α, IL-6 and hsCRP) as cardiovascular risk factors." (PMID 24736687, 2014). "Inflammatory mediators, including C-reactive protein (CRP), interleukin-6 (IL-6), IL-1β, and tumour necrosis factor α (TNFα), are systemically elevated in obesity in animal and human models." (PMID 24967364, 2014). "Recently, progranulin was identified as a key adipokine mediating high fat diet-induced insulin resistance and obesity through interleukin-6 (IL-6) in adipose tissue." (PMID 24417980, 2014). "Obesity and HFD significantly shift intestinal microbiota and increased BMI is associated with altered, less diverse microbiomes and elevated IL-6 in breast milk." (PMID 25212412, 2014). "IL-6 is another cytokine that plays an important role in the development of insulin resistance in obesity." (PMID 24733068, 2014). "This study is the first to show that dietary fat intake modulates the relationship between the IL-6 −174 G>C, IVS3 +281 G>T and IVS4 +869 A>G polymorphisms on obesity and serum lipids in black and white SA women." (PMID 24962479, 2014). "Recently, it has been assessed that IL-1β is an instigator of the pro-inflammatory response in obesity via production of additional pro-inflammatory cytokines, such as IL-6." (PMID 25548896, 2014). "Obesity is associated with basic systemic inflammation, characterised by an increase in pro-inflammatory markers such as TNF-α and IL-6." (PMID 25429679, 2014). "MCP-1 and IL-6 are inflammatory cytokines which have been shown to be increased in both obesity and cancer." (PMID 25026276, 2014). "Obesity-related cytokines, such as IL-6, TNF-α, as well as adiponectin, visfatin, and leptin play important roles in the development of NAFLD, causing ROS-mediated hepatocellular injury." (PMID 25548896, 2014). "Specifically, IL-6 levels are higher in obesity, and their production is 2-3 times higher in visceral fat compared with subcutaneous fat." (PMID 25538852, 2014). "IL-6 contributes to chronic inflammation in conditions such as obesity and studies have identified elevated IL-6 levels in obese individuals." (PMID 24772421, 2014). "IL-6 is a mediator of the acute inflammatory response and contributes to chronic inflammation in obesity." (PMID 24772421, 2014). "Studies have shown that the secretion and expression of IL-6 are directly proportional to the degree of obesity, glucose intolerance, and insulin resistance." (PMID 25309775, 2014). "At the systemic level, obesity is associated with elevated pro-inflammatory cytokines TNF-a and IL-6, NEFA and basal concentrations of insulin." (PMID 24722524, 2014). "Recently, it has been demonstrated that obesity is associated with a low-grade inflammatory process, characterized by increased circulating levels of proinflammatory cytokines such as TNF-α, IL-6, and acute-phase proteins (CRP)." (PMID 24741576, 2014).
Obesity (continued). "Several reports have shown increased TNF-α, IL-6, resistin and leptin expression in obesity, type 2 diabetes, cardiovascular disease and metabolic syndrome." (PMID 24481132, 2014). "IL-6 is a novel adipokine which influences the development and evolution of obesity and insulin resistance." (PMID 25309775, 2014). "The aim of this study was to evaluate the association between obesity, measures of body fat content, and serum TNF-α, IL-6, and IL-10 in cSLE." (PMID 24741576, 2014). "We used human adipose tissue biopsies to study the relationship of MAP3K8 expression with markers of obesity and expression of pro-inflammatory cytokines (IL-1β, IL-6 and IL-8)." (PMID 24586913, 2014). "Increased levels of MCP-1, IL-6 and VEGF indicated the presence of inflammation that is associated with obesity and cancer." (PMID 25026276, 2014). "Since cytokines (MCP-1 and IL-6) and the angiogenic factor VEGF promote ovarian cancer and are also linked with obesity, we examined these factors in plasma and ascitic fluids isolated from all groups." (PMID 25026276, 2014). "In obesity, the major source of circulating IL-6 is the adipocyte as well as adipose tissue macrophages." (PMID 24835211, 2014). "Although these long duration studies demonstrated obesity and insulin resistance in the IL‐6 KO mice, the experimental designs utilized overnight fasts and larger glucose doses to induce more robust effects." (PMID 24997069, 2014). "TNF-α and IL-6 are the cytokines that are known to be expressed during inflammatory condition and are elevated in obesity-related inflammatory diseases." (PMID 25006525, 2014). "In other words, TNF-α, as an important pathophysiological culprit in obesity, stimulates IL-6 release." (PMID 24563869, 2014). "Another theory for explaining the increased amounts of IL-6 in obesity and insulin resistance states is that elevated levels of IL-6 are a secondary defense response to higher amounts of TNF-α." (PMID 24563869, 2014). "ATDCs express higher levels of IL-6, TGF-β, IL-23 that are essential cytokines for Th17 cells proliferation or differentiation, giving us a new explanation for obesity adipose tissue inflammation that is caused by Th17 cells." (PMID 24642966, 2014). "A recent study has shown that IL-6 can inhibit insulin signaling in hepatocytes, and insulin resistance is a potential link between obesity and cancer development." (PMID 23819063, 2013). "The fact that IL-6 was higher in the low-fat fed animals compared to the high-fat fed animals was an unexpected finding as obesity and type 2 diabetes are connected to an increase of low-grade inflammatory cytokine such as IL-6." (PMID 24369539, 2013). "Low-grade inflammation (LGI) is a central phenomenon in the genesis of obesity and insulin-resistance characterized by IL-6 in human serum." (PMID 24073286, 2013). "MCR1/CD68 ratio increased significantly after weight loss in parallel to adipogenic genes, such as FASN, ADIPOQ, IRS1 and SLC2A4, whereas LEP (an obesity gene marker) and IL6 (an inflammatory marker) decreased." (PMID 23951013, 2013). "Obesity contributes to metabolic dysfunction, including increases in circulating cytokines (IL-6, IL-1, and TNF), a decrease in protective factors, such as adiponectin, and communication between cells in inflammatory and metabolic diseases." (PMID 23533315, 2013). "Obesity is a chronic inflammatory condition, which enhances the risk of CVD and is associated with various inflammatory cytokines (TNF-α and IL-6)." (PMID 24324381, 2013). "Possible mechanisms of this obesity-induced renal damage are fat tissue-derived factors detrimental to renal function, such as tumor necrosis factor-α, interleukin-6 and plasminogen activator inhibitor-1." (PMID 24225117, 2013). "IL-6 expression was known to be activated by proinflammatory IKKβ/NFκB signalling pathway which is thought to contribute to the development of obesity-induced insulin resistance." (PMID 23861558, 2013).
Obesity (continued). "IL-6 appears to play a dual role in skeletal muscle by mediating impaired insulin action in obesity and facilitating increased fuel metabolism during exercise." (PMID 23431467, 2013). "C-reactive protein (CRP) and IL-6 are other biomarkers of systemic inflammation, which are increased in obesity." (PMID 24025484, 2013). "In this regard, obesity-promoted hepatocellular carcinoma development was dependent on increased production of the cytokines TNF-α and IL-6, which cause hepatic inflammation and activation of the oncogenic transcription factor STAT3." (PMID 24106481, 2013). "In our study, we found that IL-6 levels were higher in patients with both diabetes and obesity than in those with diabetes and normal-weight and those with obesity and normal glucose tolerance." (PMID 23476101, 2013). "Levels of IL-6 correlate with weight, BMI, waist/hip circumference, waist/hip ratio, and CRP concentration implicating this cytokine in obesity-associated inflammation." (PMID 23819063, 2013). "In summary, obesity in mice is associated with upregulated expression of ANXA1 in adipose tissue and this occurs in a leptin- and IL-6-independent fashion." (PMID 24312665, 2013). "There is evidence of increased circulating CRP and IL-6 levels in COPD whereas in OSA obesity is a major confounding variable and the evidence of an independent relationship between OSA and CRP/IL-6 levels is less clear." (PMID 24256627, 2013). "Interleukin-6 levels are elevated in obesity, likely due to greater WAT IL-6 secretion; and are associated with IR and T2D risk." (PMID 23675368, 2013). "Cytokine IL-6 is correlated with insulin resistance in subjects with obesity and is inducible through TLR-4 receptor activation." (PMID 24453416, 2013). "Related to obesity and type 2 diabetes, circulating levels of IL-1β were demonstrated to predict Type 2 diabetes when in conjunction with circulating IL6, suggesting a potential role for circulating IL-1β levels (though not as sole factor)." (PMID 23341960, 2013). "Obesity also contributes to bone loss; splenic T cells from obese mice exhibit increased expression of TNF-alpha, Interleukin-6, and Interleukin-1 beta, and bone marrow from these mice have increased proportions of activated memory T cells." (PMID 23474627, 2013). "The circulating levels of several adipocytokines, such as TNF-α, IL-6, MCP-1, leptin, and PAI-1, are elevated in obesity and are reduced with weight loss." (PMID 23690838, 2013). "TNF-α, in concert with IL-6, promoted hepatosteatosis and steatohepatitis, thus favoring obesity-enhanced HCC." (PMID 23533994, 2013). "The tumor-promoting cytokines IL-6 and TNF caused by obesity are involved in the development of hepatic inflammation and steatosis." (PMID 27335818, 2013). "Chronically elevated IL-6 levels in obesity have been considered to contribute to systemic insulin resistance by inducing the expression of suppressor of cytokine signaling 3 in adipose tissue and liver." (PMID 23555753, 2013). "Elevated IL-6 levels have been reported in both adipose tissue and obesity in states of obesity and insulin resistance." (PMID 23431467, 2013). "The second candidate explaining a mechanism for the higher prevalence of destructive periodontal diseases in obesity or metabolic syndrome is interleukin 6 (IL-6)." (PMID 24068858, 2013). "In this study, we demonstrated the significant correlations between indices of obesity and the baseline levels of pro-inflammatory markers, among which IL-6 and sTNFR2 independently predicted incident cancer development." (PMID 24205276, 2013). "These activated macrophages, along with adipocytes, produce several pro-inflammatory cytokines such as TNF-α and IL-6, resulting in numerous metabolic dysfunctions that accompany obesity, e.g., systemic inflammation and atherosclerosis." (PMID 24009719, 2013). "In adults, serum pro-inflammatory cytokines such as TNF-α and IL-6 are elevated in those with obesity and T2D relative to healthy controls." (PMID 23984304, 2013).
Obesity (continued). "As central administration of IL-6 enhances energy expenditure and decreases obesity, IL-6 can also influence obesity and insulin sensitivity through a central nervous system mechanism." (PMID 23781214, 2013). "Peripheral administration of IL-6 interrupts insulin signaling due to enhance expression of SOCS3 in hepatocytes suggesting that obesity-induced IL-6 expression mediates insulin resistance." (PMID 23781214, 2013). "This figure illustrates that the type of fatty acid consumed in the diet interacts with IL-6 genotypes to modulate measures of obesity." (PMID 23698162, 2013). "Nevertheless, while IL-6, IL-7, IL-8, MCP-1, and pigment endothelial derived factor (PEDF) are associated with obesity and insulin resistance, these proteins are contraction-regulated myokines, and only for IL-6 a beneficial effect has been described." (PMID 23861558, 2013). "Up to 35% of plasma IL-6 originates from adipose tissue, and other cytokines such as IL-10 and TNF-α are also reported to be elevated in obesity and linked to a wide range of metabolic complications." (PMID 23951156, 2013). "This review examines interactions between single nucleotide polymorphisms (SNP) in the inflammatory genes tumor necrosis alpha (TNFA) and interleukin-6 (IL-6) and dietary fatty acids, and their relationship with obesity and serum lipid levels." (PMID 23698162, 2013). "IL-6, MCP-1, resistin, and TNF-α are associated strongly with obesity-induced inflammation and obesity-related pathologies." (PMID 24049664, 2013). "Adipose tissue is a major contributing factor to systemic inflammation, with adipose tissue generating approximately one third of the circulating pro-inflammatory cytokine IL-6, with estimates likely varying across obesity status." (PMID 23844105, 2013). "Obesity is proposed as a chronic low-grade proinflammatory state; alterations in CRP and proinflammatory cytokines such as TNF-α and IL-6 are commonly reported in obesity." (PMID 23826157, 2013). "Nevertheless, data regarding the role of IL-6 in both obesity and insulin resistance are controversial and unresolved." (PMID 24455420, 2013). "Consistent with the chronic low-grade inflammatory state of obesity, elevated concentrations of interleukin-6 (IL-6) and C-reactive protein (CRP) have been observed in obese pregnant women." (PMID 23840945, 2013). "One potential mechanism linking obesity with HCA formation includes increased levels of adipokines such as IL-6." (PMID 23509632, 2013). "Obesity causes lipotoxicity and adipose tissue dysfunction with excessive production of adipokines like tumor necrosis factor-α (TNF-α) and interleukin 6 (IL-6) IL-1β, all of which are implicated in heart failure and related cardiometabolic complications." (PMID 24454978, 2013). "We were next interested in potential effects of a sedentary lifestyle (obesity and low lean body mass) and hormones influenced by adiposity (IL-6, adiponectin, leptin) on bone density." (PMID 22455440, 2012). "The unbalance between IL-6/TNF-α levels and IGF-I levels in the elderly directly accounts for the loss of fat-free mass suggesting that obesity and sarcopenia are highly inflammation dependent." (PMID 23091306, 2012). "For instance, IL-6 production by monocytes and macrophages in adipose tissue increased during obesity, and is believed to contribute to development of insulin resistance in both humans and animals." (PMID 23049932, 2012). "Obesity-related elevation in proinflammatory molecules, including tumor necrosis factor-α and interleukin-6 are also believed to contribute to the development of both DM and metabolic syndrome." (PMID 22898260, 2012). "Given that chronic inflammation in diet-induced obesity is associated with lipid metabolism, we next measured the plasma levels of proinflammatory cytokines, including TNF-α, IL-6, monocyte chemoattractant protein 1 (MCP-1) and interferon γ (IFN-γ)." (PMID 22720061, 2012).